CRP (C-reactive protein)
Diseases named in the same sentence as CRP in open-access papers (continued):
Sharing a sentence is not in itself a finding about the gene and the disease.
leukocytosis (continued). "The same findings were determined in case of post-treatment values of leukocytosis and serum CRP (leucocytes: 15,672.78 ± 3582.62/mm3 versus 12,177.78 ± 2076.41/mm3, p < 0.001; CRP: 88.30 ± 56.34 mg/L versus 63.49 ± 44.02 mg/L, p = 0.041)." (PMID 38138232, 2023). "Concerning the laboratory profiles, the presence of hyperglycemia, leukocytosis, and high inflammatory markers (e.g., CRP and fibrinogen) at admission was directly correlated with the need for antibiotic administration." (PMID 36671345, 2023). "Laboratory tests revealed leukocytosis, neutrophilia, lymphopenia, elevated C-reactive protein, sedimentation rate, ferritin, and B-type natriuretic peptide." (PMID 37153258, 2023). "Univariate and multivariate models were designed to test the prognostic value of inflammatory markers (CRP and leukocytosis) in predicting clinical outcomes (modified Rankin score >2) and all-cause mortality 90 days after MT." (PMID 37360331, 2023). "Physical examination and laboratory investigations showed leukocytosis, anemia, and elevated levels of C-reactive protein." (PMID 37284391, 2023). "During labor the mother presented with fever (38.1 °C), leukocytosis with neutrophilia and elevation of C-Reactive protein." (PMID 40041280, 2023). "Our population was indifferent from those reported internationally, including our demographic data that it is more prevalent in males, had high CRP level, anemia, leukocytosis and thrombocytosis." (PMID 37848930, 2023). "she had tenderness all over her muscle and arthritis both elbows,wrists, and The laboratory values were as follows: WBC 36 X103; Hb 12 g/dL; hematocrit 35.6%; platelets 787X103;blood film leukocytosis with severe neutrophilia,CRP 235mg/dL,ESR 80mm\hr." (PMID 37848930, 2023). "Currently, leukocytosis and raised CRP levels are used clinically to diagnose, stratify severity and predict clinical progress and operative difficulty in AC." (PMID 37109763, 2023). "The laboratory test results indicated leukocytosis with a white blood cell count of 13,000/cm2, C-reactive protein (CRP) levels were at 116 mg/L, troponin levels at 32 ng/L, and creatinine levels at 60 μmol/L." (PMID 37264442, 2023). "All blood tests showed inflammatory parameters such as leukocytosis with neutrophilia and elevated C-reactive protein (C-reactive protein)." (PMID 36173718, 2023). "Laboratory investigations revealed agranulocytosis and moderate leukocytosis were detected in the whole blood countwith increased C reactive protein (CRP)." (PMID 37720286, 2023). "Initial laboratory workup showed leukocytosis, elevated erythrocyte sedimentation rate, C-reactive protein, serum ferritin, and serum aldolase level with normal creatinine kinase." (PMID 37601998, 2023). "Patients with a normal serum amylase level were compared to patients with POH alone; to patients with POH, leukocytosis, or CRP elevation; or to patients with combination of all three conditions." (PMID 36746822, 2023). "One common finding of recent studies evaluating postoperative predictive factors of complications is that CRP is a more sensitive predictor of severe complications than leukocytosis." (PMID 37662605, 2023). "Recurrent panniculitis around eyelids, shin, and forearms, in association with leukocytosis, and elevated ESR and C-reactive protein (CRP) led to treatment with treatment with JAK inhibitor (JAKi), tofacitinib at 4 years of age." (PMID 37600812, 2023). "Laboratory tests showed anemia, mild leukocytosis, thrombocytosis, elevated C-reactive protein (CRP), and elevated liver enzymes." (PMID 37664365, 2023). "The blood count showed leukocytosis, lymphopenia (characteristics of the COVID-19 infection), and increased inflammatory markers, namely CRP, D-dimer, ferritin, and IL-6." (PMID 38313184, 2023). "Laboratory findings showed anemia, leukocytosis with neutrophilia, thrombocytopenia, elevated levels of CRP, ALT, AST and ESR." (PMID 37848930, 2023).
leukocytosis (continued). "In routine practice, clinicians use raised serum white blood cell count (WBC), i.e., leukocytosis and C-reactive protein (CRP) levels to aid diagnosis, stratify severity and predict clinical progress and operative difficulty in AC management." (PMID 37109763, 2023). "On Days 8 and 9, the patient had repeated episodes of febrile body temperature, accompanied by leukocytosis in full blood count on Day 7, although her CRP had dropped from 141.8 to 6.6." (PMID 37109729, 2023). "Complementary exams at the emergency department showed leukocytosis and elevated C-reactive protein." (PMID 37182090, 2023). "The most prevalent anomalies, which were also observed in our patient, were leukocytosis, high alanine transaminase/aspartate transaminase, and bilirubin levels, and increased CRP levels." (PMID 37928704, 2023). "Laboratory tests revealed leukocytosis (18.36*109/L) with elevated neutrophilia (16.05*109/L) and C-reactive protein level (115.8 mg/L)." (PMID 37565858, 2023). "Leukocytosis and elevated CRP were present in several PwCF at baseline due to chronic infection and/or CF-related inflammation." (PMID 36875141, 2023). "CRP was measured in seven (46.7%) of the female children, being altered in three (42.9%), and leukocytosis was reported in two (13.3%)." (PMID 37110339, 2023). "Laboratory tests revealed signs of acute inflammation, including leukocytosis, elevated levels of C-reactive protein (CRP), and reactive thrombocytosis." (PMID 37933350, 2023). "Frequent laboratory findings included elevated lactate, LDH and CRP concentrations as well as degraded blood pH values and leukocytosis." (PMID 37561214, 2023). "Laboratory findings during flares include leukocytosis, elevated acute-phase reactants (CRP, serum amyloid A, haptoglobin, fibrinogen), and an increased erythrocyte sedimentation rate (ESR)." (PMID 36876221, 2023). "Upon admission, laboratory tests revealed leukocytosis with neutrophilia, elevated C-reactive protein, procalcitonin, lactate, urea, and creatinine." (PMID 37123809, 2023). "Leukocytosis and a high D-dimer show good diagnostic performance; however, a high INR and elevated CRP performance were fair, and an elevated ferritin level was poor." (PMID 37235308, 2023). "The laboratory studies showed leukocytosis, highly elevated c-reactive protein, and modified coagulation tests (due to anticoagulant treatment)." (PMID 37510971, 2023). "The clinical presentation overlaps with that of other abdominal and pelvic infections, the patient presenting with progressive lower abdominal pain with fever and elevated C-reactive protein (CRP) with leukocytosis." (PMID 37222834, 2023). "Laboratory examination showed the following results: leukocytosis (17.08*109/L) with neutrophilia (15.15*109/L) and elevated C-reactive protein level (111.7 mg/L)." (PMID 37565858, 2023). "Biological investigations showed an inflammatory response pattern with elevated C-reactive protein levels (median 129.7 mg/L), leukocytosis in 64.3% of cases, and neutrophilia (69.4%)." (PMID 37894143, 2023). "These include symptoms such as pain, tachycardia, fever, oliguria, ileus, diarrhoea and leukocytosis, in combination with elevated blood levels of C-reactive protein (CRP)." (PMID 37486461, 2023). "All patients showed elevated inflammatory markers (leukocytosis, elevated C-reactive protein, and ferritin)." (PMID 36760557, 2023). "The laboratory findings from that time indicated leukocytosis, elevated c-reactive protein, and modified coagulation tests." (PMID 37510971, 2023). "Laboratory findings characteristic of HFRS include thrombocytopenia and leukocytosis, as well as elevated levels of C-reactive protein (CRP), urea and creatinine." (PMID 38004329, 2023). "The common laboratory findings include anaemia due to chronic inflammation, intestinal bleeding, leukocytosis, thrombocytosis, elevated acute phase reactants like C-reactive protein (CRP), and elevated erythrocyte sedimentation rate (ESR)." (PMID 37842480, 2023).
leukocytosis (continued). "We noticed leukocytosis, thrombocytosis, and elevated serum CRP at three months after the surgery, with variable production of different cytokines in response to the stimuli." (PMID 38275389, 2023). "Laboratory findings in cytokine storm include leukocytosis, leucopenia, anemia, thrombocytopenia, and elevated levels of C-reactive protein (CRP), ferritin, triglycerides, and D-dimer." (PMID 35208467, 2022). "Blood tests were unremarkable except for leukocytosis with neutrophilia, which were elevated in CRP." (PMID 35627798, 2022). "Of those, 622 (7.7%) patients had elevated CRP combined with leukocytosis, whereas WBC and CRP were normal in 5′177 (64.3%) patients." (PMID 35622132, 2022). "Other studies found biological factors such as leukocytosis, lymphocytopenia, albumin levels, serum lactate dehydrogenase levels, and CRP levels to carry predictive value." (PMID 35501514, 2022). "We found a positive correlation between phosphoric acid and well-studied markers of inflammation in IBD, such as CRP and leukocytosis." (PMID 36235613, 2022). "This association was even more pronounced in the subgroup of patients with combined leukocytosis and elevated CRP." (PMID 35622132, 2022). "In 14/16 cases in dogs with bacterial discospondylitis the level of CRP was elevated (100.7 μg/mL), in contrast to 12 dogs with pyrexia and 6 experiencing leukocytosis." (PMID 36290272, 2022). "His blood tests showed leukocytosis (18,300/μL), eosinophilia (26.5%), and high C-reactive protein levels (18.12 mg/dL)." (PMID 36551171, 2022). "His laboratory abnormalities showed leukocytosis, neutrophilia, lymphopenia, thrombocytopenia with high levels of ferritin, D-dimer, CRP, AST, ALT, total and direct serum bilirubin, and serum creatinine." (PMID 36553314, 2022). "Biochemical investigations were significant for leukocytosis of 17.5×103/mm3, D-dimer of 3680 ng/mL, CRP 257 mg/L, and LDH 3434 U/L." (PMID 36505163, 2022). "Other reported features of YAOS include sicca-like symptoms, most commonly periorbital swelling, lower extremity swelling, oral ulcers, elevated erythrocyte sedimentation rate/C-reactive protein, leukocytosis, pericarditis, and pleuritis." (PMID 36186408, 2022). "Laboratory studies revealed leukocytosis (white cell count 29.7 × 109/L), hemoglobin of 11.1 g/dL, normal platelet count (230 × 109/L) and raised C-reactive protein (CRP) (30 mg/dL)." (PMID 36557034, 2022). "Other adverse events were reported and included deep vein thrombosis in one patient, pain in 10 patients, leukocytosis in 10 patients, and increased C-reactive protein levels in 10 patients." (PMID 36522336, 2022). "Systemic inflammatory response syndrome with leukocytosis and increased values of C-reactive protein (CRP), tumor necrosis factor alfa, interleukin-6, and others are observed in up to 60% of patients with aSAH." (PMID 35208646, 2022). "For the inflammatory/infectious markers on admission, leukocytosis >15 × 109/L was found in 18.9%, C-reactive protein >40 mg/L in 53.3%, and procalcitonin >0.5 ng/ml in 29.0%." (PMID 36531535, 2022). "The mean values and standard deviations (SDs) of pre-procedural leukocytosis and serum CRP were 15,345.23 ± 2340.4/mm3 and 123.32 ± 46 mg/L, respectively." (PMID 35630036, 2022). "83.3% (10/12) maternal listeriosis patients had leukocytosis, and 91.7% (11/12) had elevated CRP levels." (PMID 35346105, 2022). "On admission, tests revealed leukocytosis, an increase in C-reactive protein (CRP), and an increase in erythrocyte sedimentation rate." (PMID 35089243, 2022). "As first finding, high levels of cfDNA were associated with other inflammatory markers such as C-Reactive Protein (CRP), leukocytosis, and granulocytosis." (PMID 36033451, 2022). "Laboratory evaluation showed mild anemia, leukocytosis with neutrophil predominance, hyponatremia, elevated C-reactive protein (CRP), and an elevated sedimentary rate." (PMID 36336675, 2022).
leukocytosis (continued). "Leukocytosis more significant than 10 × 103/mm3 (52.6%, n = 70) and CRP more potent than 5 mg/L (44.5%, n = 40) were constant." (PMID 35204926, 2022). "Laboratory tests demonstrated leukocytosis (11.68 × 109/L), normal percentage of neutrophils, and an elevated hs-C-reactive protein (69.06 mg/L)." (PMID 35475804, 2022). "Biologically, IMTs can induce inflammation with leukocytosis, neutrophilia and elevation of C-reactive protein and erythrocyte sedimentation rate." (PMID 35954326, 2022). "Blood tests revealed leukocytosis (12,800/μL), eosinophilia (30.1%), and elevated C-reactive protein levels (7.39 mg/dL)." (PMID 36551171, 2022). "Initial laboratory results revealed high level of inflammatory markers, including C-reactive protein of 156.8 mg/l, erythrocyte sedimentation rate of 100 mm/hour, procalcitonin of 13.84, leukocytosis with neutrophilia, and lymphopenia." (PMID 36192799, 2022). "Followin initiation of therapy with piperacillin/tazobactam, the CRP fell to 74 mg/L (day 14) and there was a mild persisting leukocytosis (12.14 × 103)." (PMID 35974355, 2022). "Risk factors for IVIG resistance in patients with KD have been identified as prolonged fever, young age, leukocytosis, thrombocytopenia, high CRP levels, and/or elevated liver transaminases." (PMID 36291524, 2022). "His lab work was remarkable for mild leukocytosis (12.9 × 109/mL), neutrophilia (80%), elevated C-reactive protein (CRP) (90 mg/L), elevated erythrocyte sedimentation rate (33 mm/hr)." (PMID 35616878, 2022). "Data obtained from all the studies suggest that inflammatory markers were elevated in a majority of cases, with reported leukocytosis and elevated CRP, and percentages from 81.8% to 98.2% for CRP." (PMID 36016309, 2022). "Acute phase reactants, especially ESR and CRP, are raised and leukocytosis is commonly seen in acute KD." (PMID 35743997, 2022). "The common laboratory findings among pregnant women were lymphopenia, leukocytosis, and elevated levels of C-reactive protein." (PMID 36694500, 2022). "The findings in our series show leukocytosis with neutrophilia and discrete increase in CRP values in all cases." (PMID 35202185, 2022). "Blood tests revealed leukocytosis with neutrophilia, high C-reactive protein (CRP), and liver dysfunction." (PMID 35116046, 2022). "Most patients presented with leukocytosis, lymphopenia, high values of C reactive protein, and D-Dimer." (PMID 35235613, 2022). "Blood work revealed leukocytosis with predominance of neutrophils at 23 × 109/L, microcytic anemia with hemoglobin at 95 g/L, and markedly elevated C-reactive protein (CRP) at 321 mg/L." (PMID 36510304, 2022). "Laboratory tests revealed leukocytosis with neutrophil predominance, elevated D-dimer, erythrocyte rate, and C-reactive protein." (PMID 36120210, 2022). "On laboratory evaluation, leukocytosis, with dominancy of neutrophils, anemia, and thrombocytosis in addition to increased erythrocyte sedimentation rate and C-reactive protein were the most noticeable findings." (PMID 36714641, 2022). "Laboratory studies revealed leukocytosis with 19,500/mm3 and elevation of C reactive protein to 22 mg/L." (PMID 35714394, 2022). "Complete blood count (CBC) is an essential part of diagnosis in children with suspicion of appendicitis, leukocytosis, C-reactive protein (CRP), erythrocyte sedimentation rate (ESR), and hyponatremia can help the diagnosis." (PMID 36676645, 2022). "Laboratory results revealed leukocytosis, thrombocytosis, and elevated inflammatory markers (CRP 24 mg/dl and fibrinogen 599 mg/dl) with normal CPK." (PMID 35012585, 2022). "We suggest considering high CRP level and leukocytosis as predictors of abdominal emergencies following bariatric surgery (Weak recommendation based on low level of evidence 2C)." (PMID 36167572, 2022).
leukocytosis (continued). "The laboratory findings include elevated CRP (C-reactive protein) and D-dimers, leukocytosis or leukopenia, anemia, thrombocytopenia and prominent levels of serum inflammatory cytokine levels, Interferon-gamma, IL-6, IL-1 and IL-10." (PMID 35629072, 2022). "The two groups were initially statistically comparable with respect to leukocytosis and blood CRP values." (PMID 35149701, 2022). "An exploratory laparoscopy should be performed as soon as possible in the presence of suspected OT with leukocytosis, vomiting, and CRP ≧ 40 mg/L." (PMID 35204926, 2022). "Laboratory analysis showed leukocytosis (26 × 103/μL) and high C-reactive protein (CRP) levels (155.4 mg/L)." (PMID 36013476, 2022). "Blood tests revealed mildly elevated liver enzymes, increased amylase, marked leukocytosis, severe anemia, and high CRP and ESR." (PMID 36111059, 2022). "The primary laboratory findings among pregnant women were lymphopenia, leukocytosis, and elevated CRP concentrations." (PMID 36694500, 2022). "Many studies have reported on other prognostic markers for SARS-CoV-2, such as leukocytosis and C-reactive protein (CRP), and blood urea nitrogen combined with D-dimer." (PMID 36431059, 2022). "course was introduced, for suspected otitis, further supported by leukocytosis and elevated blood C reactive protein (CRP)." (PMID 36245466, 2022). "In previous studies, leukocytosis (= elevated WBC) and elevated CRP were associated with more severe strokes and larger infarct volume in the general stroke population." (PMID 35622132, 2022). "Second, the risk of ischemic ovary torsion increased when the OT patient experienced vomiting, leukocytosis, and elevated CRP." (PMID 35204926, 2022). "Laboratory routine blood tests showed elevated SCr (11.77 mg/dL), urea (237 mg/dL), and potassium (6.6 mEq/L) as well as leukocytosis (13.200/μL), with increased polymorphonuclears and high C-reactive protein (CRP) levels (95.6 mg/L)." (PMID 35949914, 2022). "Laboratory assessment showed leukocytosis (15,72 G/l), thrombocytosis (801 G/l) as well as elevation of CRP (40 mg/l), soluble IL2-receptor (1928 kU/l) and IgG (1840 mg/dl)." (PMID 36405723, 2022). "Patients with liver cirrhosis suffer from chronic inflammation with elevated inflammatory markers, such as C-reactive protein (CRP), and leukocytosis." (PMID 35628913, 2022). "The remaining cases were clinically diagnosed as infectious diseases due to leukocytosis, high CRP levels and good response to antibiotic treatment." (PMID 35115619, 2022). "Other documented laboratory abnormalities include hypoalbuminemia, increased C-reactive protein (CRP), and hematologic abnormalities such as anaemia, leukocytosis, leukopenia, and thrombocytopenia." (PMID 35774682, 2022). "Laboratory testing demonstrated leukocytosis with left shift and significant elevation of C-reactive protein." (PMID 36581904, 2022). "Laboratory data on the day of arrival at the hospital showed leukocytosis (19,400/uL) and a high CRP level (78.49 mg/L)." (PMID 35807115, 2022). "On admission, he subsequently developed an insidious onset of muscle rigidity and autonomic instability, and laboratory work-up was significant for leukocytosis, transaminitis, and elevations in creatinine phosphokinase, lactate, and C-reactive protein." (PMID 36381714, 2022). "Blood tests showed leukocytosis and increased high sensitivity troponin I and C-reactive protein (CRP)." (PMID 36654539, 2022). "Positive correlations between the length of stay and leukocytosis, neutrophilia, N/L ratio, and CRP level were shown in patients with odontogenic infections requiring hospitalization." (PMID 35659711, 2022). "Poor outcome (64.0% vs 36.5%) and mortality (28.5% vs 10.3%) were more frequent in patients with combined leukocytosis and elevated CRP." (PMID 35622132, 2022).